IL1A (interleukin 1 alpha)
Diseases named in the same sentence as IL1A in open-access papers (continued):
Sharing a sentence is not in itself a finding about the gene and the disease.
tumor (continued). "Conclusively, aberrant IL1A induction elicited tumor growth and invasiveness in the TNBC models." (PMID 34203721, 2021). "The results showed that exogenous and autocrine IL-1α could significantly increase the secretion of CXCL12 by the important stromal fibroblasts in tumor microenvironment, which could be inhibited by interleukin 1 receptor antagonist (IL-1Ra)." (PMID 34930323, 2021). "Our finding suggested that cytokines such as IL-1α, IL-1β has been transcriptionally increased in which it may subsequently be secreted and promote an inflamed tumor microenvironment." (PMID 34789798, 2021). "In both tumor types pFUS increased IL1α, IL1ß, IL2, IL6, IL12p40, IL15, IL17, TNFα, and VCAM." (PMID 33801627, 2021). "In another study, coculture of cancer associated fibroblasts (CAFs) with pancreatic ductal adenocarcinoma cells (PDAC) resulted in upregulation of IL-1α and other inflammatory factors, creating an inflammatory tumor microenvironment suitable for tumor survival and progression." (PMID 33430381, 2021). "Moreover, IL-1α was found to be the key in the formation and maintenance of this inflammatory tumor microenvironment as blockage of IL-1α alone significantly ablated the production of other inflammatory factors." (PMID 33430381, 2021). "The expression of T cell cytotoxicity (CD3G, CD3E, CD4, GZMA, PRF1 and TBX21), B cell MHC II and immune exhausted-related genes were abundant in metastatic sites; while MHC I inflammation related genes (HLA-B, HLA-C and IL-1A) were mostly higher in primary than recurrent tumor sites." (PMID 33476333, 2021). "However, in some cases, IL-1α can also enhance the immunogenicity of malignant tumor cells, thus reducing the invasiveness of tumors." (PMID 34930323, 2021). "The gene expression of multiple inflammatory markers in the heart was significantly upregulated in tumor-bearing mice as compared to tumor-free mice, including the pro-inflammatory cytokines IL-1α, IL-1β, IL-6, and TNF- α and the inflammatory chemokines Mcp-1, Cxcl1, and Cxcl10." (PMID 34445729, 2021). "IL1A was enriched in both scaffolds and liver metastases compared with the primary tumor." (PMID 33782087, 2021). "Mechanistic studies have further revealed that pro‐tumorigenic SASP is mediated at both the transcriptional and translational level by mTOR, which promotes an IL‐1α/NF‐κB feedback loop for SASP production that led to tumour growth in mouse xenografts of prostate tumour cells." (PMID 32981205, 2021). "Moreover, IL1α depletion in CMs of macrophages enhanced proliferation and migration of SK‐N‐SH cells and blunted the tumor‐inhibiting effects of FABP4‐knockdown macrophages." (PMID 33931964, 2021). "Several signals have been demonstrated to induce specific CAF subtypes, where tissue stiffness, TGFβ signalling and spatial proximity to tumour nests induce myCAF features, whilst tumour cell-secreted IL1α drives the iCAF phenotype through the JAK-STAT pathway." (PMID 34921158, 2021). "Additionally, subjects with the lowest survival probability expressed very few immune-related genes at high levels, many of which are known to promote tumor progression, including IL1A, IL1B, and TGFB, and which were also correlated with increased FIGO stage." (PMID 33834038, 2021). "Furthermore, carcinoma-derived IL-1 (IL-1α and IL-1β) favors a transition from tumor cells into CSCs." (PMID 32635472, 2020). "Additionally, pro-inflammatory markers (e.g., IL1α and IL1β) were highly expressed at the tumour periphery, while a more anti-inflammatory phenotype (e.g., IL1RN) was observed in the tumour core." (PMID 31973030, 2020). "HPV infection was suspected in all those tumor tissues, prompting that the tumor-promoting effect of IL1A may due to HPV-mediated rearrangement of signal pathway in host cells." (PMID 32047552, 2020).
tumor (continued). "Immune cells exposed to the metastatic microenvironment upregulated gene expression of cytokines that are associated with increased angiogenesis and tumor progression, including IL-1α, and tumor proliferation, migration and recruitment of myeloid-derived suppressor cells (MDSC) such as GM-CSF." (PMID 33034643, 2020). "We proposed that the tumor-promoting effects of IL1α could be a context-dependent phenomenon and may require the presence of an immune system." (PMID 33105540, 2020). "The immune checkpoint marker TIM‐3, in addition to its negative association with sTILs %, also inversely correlated with CD68 staining grade and with whole tumor density of CD8+ and CD20+ cells, while IL‐1α only showed a significant inverse association with CD8." (PMID 33024560, 2020). "Besides, intratumoural CCL22 is induced in tumour-infiltrating DCs through cancer cell-derived IL-1α." (PMID 32680511, 2020). "However, these blockers inhibit both IL-1β and IL-1α, but IL-1α can have tumor promoting or inhibiting functions, and inhibiting this isoform together with IL-1β can have synergistic or antagonist effects, depending on the context." (PMID 32635472, 2020). "Thus, the source of inflammation is the tumor itself, since all cancer cells of epithelial origin contain IL-1α in its precursor form." (PMID 32825489, 2020). "This pro-tumoral effect associated with autophagy impairment was due to increased ROS production and NF-κB/interleukin-1 alpha/beta (IL-1α/β) signaling, resulting in inflamed TME, thus demonstrating an antitumorigenic role of Kupffer cell-associated autophagy in HCC tumor initiation." (PMID 32231206, 2020). "Interestingly, both forms of IL-1α have been shown to have potential tumor promoting effects as the pro-piece, nuclear form of IL-1 has been shown to facilitate the growth of acute T-lymphocytic leukemia cells through the activation of NF-κB and SP1." (PMID 31231372, 2019). "Afterwards, the expression levels of 12 cytokines including IL-1a, IL-1b, IL-2, IL-4, IL-6, IL-8, IL-10, IL-12, IL-17A, TNFα, IFNγ and GM-CSF in secretome of hWJ-MSCs alone as well as in supernatant of tumor cells before and after treatment with hWJ-MSCs secretome were evaluated." (PMID 31857970, 2019). "Altogether, we believe we have identified a combined high nuclear IL-1α/EGFR+ tumor expression profile as a strong prognostic biomarker for progression-free survival in OSCC patients which warrants further study in other HNSCCs and other EGFR-expressing tumors." (PMID 31320902, 2019). "In summary, we identified tumor-derived IL-1α and IL-1β as key cytokines in driving TSLP secretion by CAFs and tumor-released ASC, whose expression in PDAC correlates with reduced patients’ survival, as a relevant component in the inflammatory cascade involving activation of IL-1β secretion by TAMs." (PMID 30760333, 2019). "Kasza has reported that IL-1α serves as a pleiotropic cytokine in human cancer progression as well as various immune and inflammatory responses, and the secreted IL-1α is an active form which induces the tissue damage and tumour growth together with other regulatory factors." (PMID 30819119, 2019). "The combination treatment can induce secretion of several cytokines such as IL1a, in vitro and in vivo, which may lead to a significant and long-term anti-tumor immune response." (PMID 30781871, 2019). "Altogether, these results suggest that IL-1α in combination with cetuximab can induce a T cell-dependent anti-tumor immune response and may represent a novel immunotherapeutic strategy for EGFR-positive HNSCCs." (PMID 30890189, 2019). "As a tumor is often described as being like a “chronic wound”, the hypoxic conditions and high concentration of cytokines and growth factors IL-1α, IL-1β, IL-6, FGF-2, IGF-1, TGF-β, VEGF-A, HIF-1α, EGF, TGF-α are a likely trigger for MSCs recruitment to tumor microenvironments." (PMID 31569731, 2019).
tumor (continued). "Since IL-1 signaling may be involved in anti-tumor response, we next sought to address if increasing IL-1α expression could enhance the efficacy of cetuximab." (PMID 30890189, 2019). "However, secretable form of IL-1α in the microenvironment of tumour cells has been proved to facilitate tumour invasiveness and angiogenesis." (PMID 30819119, 2019). "Furthermore, reductions in open field locomotion in all mice exposed to a tumor (combined tumor-bearing and -resected groups) were predicted by elevated brain Il1α and Il1β gene expression (p < 0.05 in both cases)." (PMID 31019214, 2019). "Furthermore, depletion of CD4+ and CD8+ T cells significantly reversed the effect of cetuximab+IL-1α-NP suggesting that IL-1α in combination with cetuximab can induce a T cell-dependent anti-tumor immune response." (PMID 30890189, 2019). "To understand which molecules were responsible for this activity we performed experiments of THP1 activation with tumor cell supernatants in the presence of neutralizing Abs and BoxA to inhibit IL-1α, TNF-α, IL-18 and HMGB1, respectively, which are released by tumor cells." (PMID 30760333, 2019). "Given the role of IL-1 signaling in anti-tumor immune response, we hypothesized that increases in IL-1α levels would enhance tumor response to cetuximab." (PMID 30890189, 2019). "Altogether, the results presented here suggest that IL-1α in combination with cetuximab can induce a T cell-dependent anti-tumor immune response and may represent a novel immunotherapeutic strategy for EGFR-positive HNSCCs." (PMID 30890189, 2019). "Differential effects of IFN-g, IL-1a, and IL-27 on individual tumor cell lines were not due to PDL1 promoter polymorphisms." (PMID 31730010, 2019). "Given these tumor-promoting functions for IL-1α, studies have investigated whether it represents a potential therapeutic target for cancer therapy." (PMID 31231372, 2019). "Neoplastic tumours developed upon wounding these mice, but the lesions could be prevented by pharmacologically blocking the IL-1α-mediated response." (PMID 30341279, 2018). "SNAIL1 represses the production of pro-inflammatory cytokines IL-1α and TNFα and inhibits production of GM-CSF, a known stimuli of M1-like macrophages leading to a suppression of the pro-inflammatory response elicited by the tumor cells." (PMID 29593211, 2018). "Splenic IL-8 also has a strong positive correlation to tumor GM-CSF and IL-1α." (PMID 30513792, 2018). "The results also suggested that I IL-1α has a significant function in tumor metastasis." (PMID 29344744, 2018). "In addition to promoting tumour progression, by controlling Treg recruitment via CCL22 signalling, however, IL-1A mediated IL-1R1 signalling has also been reported to have anti-tumour functions." (PMID 29760166, 2018). "To determine if tumor cells are a source of these cytokines, we analysed the effect of treatment with tumor cell-conditioned medium on cytokine levels and found a very similar inflammatory profile with elevated IL-1α, IL-6, MIP-1α and G-CSF." (PMID 30532184, 2018). "Interestingly, activated T cells can enhance HSC activation, resulting in IL-6, IL1-α, and TGFβ production, thus adding to the inflammatory milieu of cytokines promoting tumor growth." (PMID 30150983, 2018). "The study of the role of IL-1α in tumor development has been focused on the secreted IL-1α." (PMID 28152513, 2017). "In a Th1 microenvironment, proinflammatory cytokines (e.g., IL-6, IL-1α, and IL-1β) may contribute to tumour eradication by attracting leucocytes from the circulation and by increasing CD4 + T cell activity." (PMID 29089667, 2017). "In contrast, the proinflammatory cytokines IL-6, IL-1α, and IL-1β may appear more unexpectedly as chronic inflammation related to the tumour." (PMID 29089667, 2017). "During tumor development, secreted IL-1α was found to be increased and the secreted IL-1α in the tumor microenvironment could lead to exacerbation of tumor growth." (PMID 28152513, 2017).
tumor (continued). "Notably, we experimentally demonstrate that maintenance of tumour sphere-forming cells are dependent on both IL1α/IL1β and cellular ROS homeostasis conveyed by GCLM, which are all glucose-inducible genes." (PMID 28300060, 2017). "During the tumor progression of myeloma within the bone marrow, indeed, both interleukin (IL)-1α and IL-1β secreted by MM cells stimulate the stroma to produce IL-6 through the linkage of the early growth response (EGR)-1 protein to the promoter of IL-6 (pIL6)." (PMID 28962646, 2017). "Meanwhile propiece IL-1α should be generated by the calpain cleavage and the major nuclear form of IL-1α may be the propiece IL-1α during tumor development." (PMID 28152513, 2017). "Our findings further underscore the important role of glucose in tumour sphere-forming cells and provide a revolutionized view for glucose in the maintenance of tumour sphere-forming cells through activating and maintaining the expression of IL1α/IL1β and GCLM." (PMID 28300060, 2017). "IL-1α and IL-1β can be produced by tumor as well as stromal cells." (PMID 27630452, 2016). "Moreover, if the BF-rTK survived in the tumor via IV administration, it would be assumed that BF-rTK stimulated the production of higher concentrations of cytokines (e.g., IL-1α, IL-1β, IL-2, IL-10, IL-17, GM-CSF, and MCP-1)." (PMID 27275821, 2016). "Similarly, although not in a calpain-dependent manner, we found that lung TAMs can release IL-1α under LPS stimulation, contributing to tumor proliferation." (PMID 27528423, 2016). "The main source of IL-1α seems to be tumor/epithelial cells." (PMID 27528423, 2016). "Tumor associated macrophages (TAM) produce cytokines like TNF –α and IL1-α which are the key regulators of cancer associated inflammation as they exert various pro-tumoral activities like monocyte guidance to tumoral tissues, growth factors for tumor cells and adaptive immune reaction suppression." (PMID 27902750, 2016). "Interestingly, IL-1α expression was down-regulated in human tumor biopsies following vemurafenib treatment." (PMID 25709607, 2015). "Thus, IL-1α can potentially amplify the pro-inflammatory DAMP signaling upon its release by dying tumor cells." (PMID 26307977, 2015). "We also show a correlation between IL-1α expression and tumor cell transmigration." (PMID 26460957, 2015). "This suggests that IL-1α stimulates vascularization, thus facilitating tumor cell transmigration." (PMID 26460957, 2015). "IL-1α produced by tumor cells effectively increased its transmigration across the endothelium." (PMID 26460957, 2015). "The effects of constitutive IL-1α expression by tumor lines were characterized." (PMID 26460957, 2015). "While IL-1α and IL-1β can have similar biological activities in recombinant or secreted form, these closely related cytokines seem to play very different roles in tumor immunology." (PMID 24416335, 2014). "In the present studies focal irradiation of the tumor reduced the Th2 (IL-4 and IL-5) responses through B cells and inflammation (IL-6, IL-17, GM-CSF, IL-1α), which was accentuated by 2-DG besides removing the systemic immunosuppression through depletion of Tregs." (PMID 25248151, 2014). "In light of these studies, IL-1α may support tumor progression depending on tumor types and their malignant properties." (PMID 24924428, 2014). "Although IL-1α and β share a receptor, they function differently in the tumor and its stroma." (PMID 28548063, 2014). "Conversely, in the HER2-negative cohort, which is different from the HER2-positive arm for the biology of the tumor, the NC treatment, and also for the immune profile at diagnosis, we observed changes in IL-1α, IL-1β, IL-2, IL-6, and GM-CSF levels already at week 12 of ED treatment." (PMID 25512030, 2014). "Interestingly, ALT-803 alone resulted in similar tumor reduction and production of urinary IL-1α, IL-1β and RANTES, which also led to the activation and proliferation of CD8a+ T-cells." (PMID 24896845, 2014).
tumor (continued). "Thus, the IL-1α-driven inflammatory activation of angiogenesis and lymphangiogenesis seems to provide a highly metastatic tumor microenvironment favorable for lymph node metastasis through cross-talk with macrophages." (PMID 24924428, 2014). "This tumor growth-promoting effect of IL-1α-pretreated MSCs can be blocked by siRNAs against TGF-β." (PMID 24502410, 2014). "The antibody-based therapy could be inhibiting IL-1α signaling and/or may be targeting tumor cells for antibody dependent cell cytotoxicity (ADCC)." (PMID 24416335, 2014). "However, E-selectin expression at the surface of endothelial cells is induced by tumor-derived IL-1α and monocyte-induced IL-1β in inflammatory metastatic sites." (PMID 25255877, 2014). "We hypothesize that IL-1α in the tumor microenvironment is immunostimulatory, rather that inflammatory, due to its localization on the surface of cells and its limited secretion, as compared to IL-1β." (PMID 23847618, 2013). "Our findings of an inhibiting role of p38MAPK inhibitors on PDAC tumor cell IL-1α expression could have the potential to affect the crosstalk between tumor cells and CAFs." (PMID 23951028, 2013). "In conclusion, better understanding the integrative role that IL-1α and IL-1β play in animal experimental models and in cancer patients, together with “IL-1 mapping” at tumor sites should pave the way for safe and efficient application of anti-IL-1 therapies at the bedside for cancer patients." (PMID 23847618, 2013). "At tumor sites, immunosuppressive effector cells, induced by excessive expression of IL-1β inhibit or mask the induction/function of anti-tumor immunosurveillance induced by tumor cell-derived IL-1α." (PMID 23847618, 2013). "In parallel, upon RUNX2 knockdown, we have observed a predominant and strong downregulation of gene nodes known to be implicated in EOC tumorigenesis (PTGS1/COX1, FGF2, IL1A, Sapk, C/ebp, SELE, UBQLN1, PSAT1, ALDH1A1, GDF15, MTHFD2), including EOC tumor invasion/metastasis (MMP1, MMP13, Creb);." (PMID 24124450, 2013). "The expression of IL-1α by tumor cells is detected in 90% of the PDAC patients and could correlate to mutations in the oncogene K-Ras as they also are present in up to 90% of the PDAC cases." (PMID 23951028, 2013). "In addition, rhIL-1RA was added to all groups in this experiment to eliminate any direct effects of IL-1α on the tumor cell migration." (PMID 23951028, 2013). "We demonstrated the anti-tumor effects of IL-1α expression by malignant cells in different experimental systems, using oncogene-transformed fibroblasts that constitutively express IL-1α, possibly due to alterations in the control of IL-1α expression induced by the oncogene." (PMID 23847618, 2013). "Thus, increased levels of IL-1α resulting from Osx inhibition gave rise to an altered tumor phenotype." (PMID 23922826, 2013). "Thus, insufficient characterization of IL-1 at tumor sites has led to some inconsistencies concerning the impact of the concerted action of IL-1α and IL-1β on the malignant process." (PMID 23847618, 2013). "However, in different tumor systems, redundant or unique patterns of IL-1α and IL-1β expression and function have been observed." (PMID 23847618, 2013). "However, IL-1α has also been reported to reduce tumor angiogenesis and participate in the regulation of immune responses." (PMID 22811704, 2012). "Consequently, in OC, IL-1β generally promotes invasiveness, tumor angiogenesis and induces immune suppression while IL-1α reduces tumorigenicity by inducing antitumor immunity." (PMID 21765834, 2011). "However, the mechanism behind IL-1α-induced tumor aggressiveness is unclear." (PMID 42013543, 2026). "A modified analysis of the NUGC-3 tumor samples showed that PC14586 administration in vivo led to changes in the expression of immune and inflammatory signaling–associated genes and gene sets (TNFSF9, CSF2, IL1A, GDF15, and TNFA signaling and inflammatory response)." (PMID 39945593, 2025).